GZMH (granzyme H)
Description:
Cytotoxic chymotrypsin-like serine protease with preference for bulky and aromatic residues at the P1 position and acidic residues at the P3' and P4' sites. Probably necessary for target cell lysis in cell-mediated immune responses. Participates in the antiviral response via direct cleavage of several proteins essential for viral replication.
Synonyms: CTSGL2; CSP-C; CGL-2; CCP-X; CTLA1
Tractability: Antibody: UniProt predicts a signal peptide or a membrane-spanning region. PROTAC: its protein half-life has been measured.
Gene: Protein-coding gene on chromosome 14 (24,606,480 to 24,609,821, reverse strand). Ensembl gene ENSG00000100450.
Subcellular location: Cytolytic granule
Pathways (Reactome):
Metabolism of proteins: Metabolism of Angiotensinogen to Angiotensins; Regulation of Insulin-like Growth Factor (IGF) transport and uptake by Insulin-like Growth Factor Binding Proteins (IGFBPs)
Gene Ontology:
Molecular function: serine-type endopeptidase activity
Biological process: apoptotic process; protein maturation; proteolysis
Cellular component: cytolytic granule; membrane
Genetic constraint (gnomAD): Loss-of-function variants: 19 observed, 19.45 expected, observed/expected ratio (o/e) 0.98, 90% interval 0.68 to 1.43. The upper end of that interval is the gene's LOEUF score, 1.43, which puts it in group 5 of 6, group 1 being the genes least tolerant of losing a copy. Missense variants: 314 observed, 292.45 expected, observed/expected ratio (o/e) 1.07, 90% interval 0.98 to 1.18. Synonymous variants: 107 observed, 108.23 expected, observed/expected ratio (o/e) 0.99, 90% interval 0.84 to 1.16.
Homologues: Orthologues: rabbit GZMH (75% identical), pig GZMH (65% identical), tropical clawed frog ctsg (39% identical). Paralogues in human: GZMB (72% identical), CTSG (57% identical), CMA1 (49% identical), KLK13 (35% identical), AZU1 (34% identical), KLK6 (33% identical).
Diseases named in the same sentence as GZMH in open-access papers:
GZMH is named in the same sentence as 70 diseases in open-access papers, as found by Europe PMC text mining. Sharing a sentence is not in itself a finding about the gene and the disease. The quoted sentences say what the papers report.
COVID-19 (8 papers, 2021 to 2025). A disease caused by infection with severe acute respiratory syndrome coronavirus 2. "Additionally, we found 44, 42, and 53 up-DEGs that were notably associated with mild, moderate, and severe COVID-19, and there were six significant common genes across three phases of COVID-19, including TCF7, GZMH, RAB5IF, CCND2, BIRC6, and NDUFAF3." (PMID 35172892, 2022). "Specifically, compared to healthy controls, genes marking effector and cytotoxic CD8 T cell profiles (GZMB, NKG7, GZMH, PRF1, and CCL5) were upregulated in severe dengue and downregulated in severe COVID-19." (PMID 38294906, 2024). "We found that NKG7, IL32, GZMA, PRF1, CST7, GZMH, and CCL5 were among the top DEG downregulated in CD3+ upon nasal Foralumab treatment of COVID-19 subjects." (PMID 36881624, 2023). "In contrast, CD4 CTL T-cells and NK-cell subsets displayed increased expression of effector activation markers (GZMB, GZMH, CCL4, XCL2) and ISGs in patients who succumbed to COVID-19." (PMID 35169146, 2022). "CD4 T-cells with cytotoxic activity (CD4 CTLs) and NK-cells displayed enhanced interferon signaling and effector activation markers (GZMB, GZMH, CCL4, XCL2) in patients who succumbed to COVID-19." (PMID 35169146, 2022).
Sepsis (4 papers, 2020 to 2025). Sepsis is defined as life-threatening organ dysfunction caused by a dysregulated host response to infection. "However, downregulated genes in sepsis NK cells similarly included cytotoxicity-related genes (GZMH, GNLY & GZMB, -1.42log2FC, -1.29log2FC & -0.48log2FC, respectively)." (PMID 41208955, 2025). "In addition, these results are strengthened by a significantly lower cytotoxic module score (calculated using the AddModuleScore function in Seurat V4 using the cytotoxic-related genes GZMH, GZMK, GZMA, GZMB, PRF1, and GNLY) in all sepsis cytotoxic cell subsets compared to bacteraemia and controls." (PMID 41208955, 2025). "Furthermore, the widespread downregulation of specific cytotoxic and cytolytic genes, including GNLY, GZMH and NKG7, across CD8+ T cells, NK cells, CD56+ T cells, MAIT cells and γδ T cells reported here was found to negatively impact survival outcomes in sepsis." (PMID 41208955, 2025). "However, at present there is not any study correlating GzmH with the regulation of the inflammatory response or sepsis, and, thus, GzmH will not be further discussed in this review." (PMID 32655547, 2020).
asthma (2 papers, 2012 to 2023). "At the locus 14q11.2, the five genes: KIAA0323, SDR39U1, CMA1, CTSG and GZMH were located within a single 220 kb LD block surrounding the tag biomarker rs4982958 which was associated with asthma in this study." (PMID 22545103, 2012). "While granzyme H remains less well studied in terms of respiratory disease, granzyme B has been implicated in e.g. chronic obstructive pulmonary disease, and fatal asthma." (PMID 37936126, 2023).
breast carcinoma (2 papers, 2018 to 2021). "GZMH has been reported as upregulated in some OC-tumor infiltrating leukocytes as well as serologically in breast cancer and this may be indicative of enhanced tumor-specific leukocyte activity in the early stages of disease." (PMID 29854310, 2018).
diabetes (2 papers, 2020 to 2024). "To assess the functional aspects of cytotoxic T cells, we calculated the cytotoxicity score for CD4 Tcyt and CD8 Tem using cytotoxic genes (PRF1, GZMH, and GZMK) and observed higher cytotoxicity scores in T2D patients compared to non-diabetes." (PMID 39072276, 2024).
Achalasia (1 paper, 2023). A disorder of esophageal motility characterized by the inability of the lower esophageal sphincter to relax during swallowing and by inadequate or lacking peristalsis in the lower half of the body of the esophagus. "We also found many pro-inflammatory factors in expanded effector T cells and effector memory T cells that were more highly expressed in achalasia than in controls, including TNF, IFNG, GZMB, and GZMH." (PMID 37542039, 2023).
atherosclerosis (1 paper, 2023). A disease characterized by the build-up of fatty material and calcium deposition in the arterial wall resulting in partial or complete occlusion of the arterial lumen. "In both PSA and atherosclerosis CD8+ C3 T cells, expression profiles displayed a similar phenotype with high expression of T cell effector genes—for example, CCL5, GZMH, GZMA, GZMK and NKG7." (PMID 38665903, 2023).
Cachexia (1 paper, 2022). Severe weight loss, wasting of muscle, loss of appetite, and general debility related to a chronic disease. "Indeed, differential gene expression analysis of CD8+ T cells showed significantly higher expression of genes representing activated state in cachexia patients, including GZMH, GZMA, NKG7, and IFNG." (PMID 36376273, 2022).
Chagas disease (1 paper, 2024). A parasitic infection caused by Trypanosoma cruzi. "CCL5 and GZMH were upregulated in Chagas disease patients, both IND-Pre and CCC-Pre versus HD." (PMID 39119291, 2024).
dementia (1 paper, 2023). Loss of intellectual abilities interfering with an individual's social and occupational functions. "Except for GZMH, top IL-7Rαlow aging genes were found to be more highly expressed in the MCI group compared to the dementia group (P-value < 0.05), implying increased expression of top IL-7Rαlow aging genes in earlier stages of AD." (PMID 38042785, 2023).
endometriosis (1 paper, 2021). The growth of functional endometrial tissue in anatomic sites outside the uterine body. "The highly differential genes between the two groups showed that C–C motif chemokine ligand 3 (CCL3) and X-C motif chemokine ligand 1 (XCL1) were significantly elevated in endometriosis while cytotoxic molecules including GNLY, GZMB and GZMH were significantly down-regulated." (PMID 34039410, 2021).
hematoma (1 paper, 2025). A hematoma is a collection of blood from a vascular structure into an extravascular space. "We found that the CD8_GNLY subcluster was increased in the peripheral blood and hematoma of ICH patients, along with high expression of effector genes such as GNLY, GZMB and GZMH." (PMID 41238793, 2025).
latent infection (1 paper, 2025). "The term-Tem subcluster, characterized by increased gene expression of multiple cytotoxic granules, including GZMB and GZMH, was dominant in the population with latent infection (IgG+IgM− group)." (PMID 40343282, 2025).
malaria (1 paper, 2021). Malaria is a serious and sometimes fatal disease caused by a parasite that commonly infects a certain type of mosquito which feeds on humans. "Similarly, in malaria these genes were either only modestly upregulated (GZMA and GZMB) or were downregulated (GZMH, GNLY and PRF1), compared to HS (P < .05)." (PMID 33793565, 2021).
Myelopathy (1 paper, 2024). Myelopathy is an descriptive term, referring to pathology leading to a neurologic deficit related to the spinal cord. "GZMH has been identified at high levels in CD8 + T cells of patients with HTLV-1 associated myelopathy/tropical spastic paralysis (HAM/TSP), which may migrate to the central nervous system (CNS)." (PMID 39228516, 2024).
osteosarcoma (1 paper, 2024). A usually aggressive malignant bone-forming mesenchymal neoplasm, predominantly affecting adolescents and young adults. "Furthermore, the two CD8 + cytotoxic clusters demonstrated upregulation of NKG7, GZMB, GZMH, GZMK, CCL3, CCL4, and CCL5, suggesting that chemotherapy amplified the cytotoxic function of CD8 + T cells, potentially enhancing their antitumor activity within the osteosarcoma tumor microenvironment." (PMID 39033089, 2024).
ovarian carcinoma (1 paper, 2022). A malignant neoplasm originating from the surface ovarian epithelium. "NKT cells strongly expressed the GZMB, GZMA, GZMH, and PRF1 genes, indicating that they promoted tumor cytotoxicity in ovarian cancer." (PMID 35935940, 2022).
Pleural effusion (1 paper, 2025). The presence of an excessive amount of fluid in the pleural cavity. "In liver metastasis BL T cells, granzyme family genes (GZMA, GZMH, and GNLY) were enriched, while pleural effusion BL T cells showed increased TFF3, AGR2, MGP, and MIF expression." (PMID 39955556, 2025).
renal fibrosis (1 paper, 2024). A final common manifestation of a wide variety of chronic kidney diseases characterized by glomerulosclerosis and tubulointerstitial fibrosis. "Logistic analysis, LASSO-based tenfold cross-validation, and gene topological analysis within Cytoscape identified four core genes (CD3G, CORO1A, FCGR2A, and GZMH) associated with renal fibrosis." (PMID 38378674, 2024). "While in this study, drawing from transcriptome and single-cell sequencing data of patients with kidney fibrosis in public databases, we identified four core genes significantly associated with renal fibrosis, namely CD3G, CORO1A, FCGR2A, and GZMH." (PMID 38378674, 2024). "Through logistic analysis, tenfold cross-validation with LASSO, and gene topological analysis in Cytoscape, we pinpointed four core genes significantly associated with renal fibrosis: CD3G, CORO1A, FCGR2A, and GZMH." (PMID 38378674, 2024).
ulcerative colitis (1 paper, 2024). An inflammatory bowel disease involving the mucosal surface of the large intestine and rectum. "The DRB1*01:03 allele—which is thought to be a risk allele for ulcerative colitis (UC) based on prior GWAS39—was associated with both UC and the expression of several inflammatory proteins such GZMA, GZMH, and IL10." (PMID 39085222, 2024).
uveitis (1 paper, 2023). An inflammatory process affecting a part of or the entire uvea. "Correspondingly, VKHD uveitis demonstrated a selective expansion of CD4+ T cell clones which were enriched in pro‐inflammatory Granzyme H+ CD4+ Tem cluster and showed TCR and Th1 pathway activation." (PMID 37720629, 2023). "In contrast, BD uveitis showed a preferential expansion of CD8+ T cell clones in pro‐inflammatory Granzyme H+ CD8+ Tem cluster, and pathway activation for cytoskeleton remodelling, cellular adhesion and cytotoxicity." (PMID 37720629, 2023).
vitiligo (1 paper, 2025). Generalized well circumscribed patches of leukoderma that are generally distributed over symmetric body locations and is due to autoimmune destruction of melanocytes. "Finally, we obtained ten matched genes (GP1BA, ANKS4B, CCDC87, CA8, HLA‐DOB, RHEBL1, NLRP7, GZMH, HERPUD1, and MAP2K1) as a vitiligo‐gene signature (VGS)." (PMID 40974370, 2025).
tumor (38 papers, 2018 to 2025). "When all tumor samples were evaluated together the correlation of GZMH, ABL1, IL-7, LY9, IL-12, SCAMP3, and CD244 were highly significant (p < 1 × 10−6)." (PMID 29587383, 2018). "It is known that cytotoxic T cells and NK cells secrete five different granzymes (GzmA, GzmB, GzmH, GzmK, and GzmH), serine proteases, and that granzyme-mediated cell death is the major pathway to kill virus-infected cells or tumor cells." (PMID 29642409, 2018). "Additionally, they continued to express cytotoxic effectors (including GZMA, GZMB, GZMH) reflective of their anti-tumor potential." (PMID 38008725, 2023). "In comparing the occurrence and development of normal tissues and tumor tissues, we found that the expression levels of genes encoding activation and cytotoxic molecules, such as GZMB, GZMH, GZMK, GZMA, and NKG7, increased significantly and had strong correlations with signs of exhaustion." (PMID 35634956, 2022). "New clonotypes appearing in blood or tumor at disease progression were enriched for genes associated with cytotoxicity or stemness (FGFBP2, GNLY, GZMH, GZMK, IL7R, SELL and KLF2), and these might be harnessed for alternative cellular therapy or cytokine therapy." (PMID 36514045, 2022). "The CD56dimCD16hi subsets of NK cells within the tumor tissue showed lower expression levels of cytotoxic genes like PRF1, GZMB, GZMA, GZMH, and GZMK compared to normal tissues." (PMID 38552055, 2024). "Consistently, the tumor-infiltrating GZMAhigh NK subcluster expressing a high level of cytotoxic genes (GZMA, GZMB, GZMK, GZMM, GZMH, PRF1, and GNLY) and FASL and TRAIL genes was most enriched in the PD-1+SMI group." (PMID 37430270, 2023). "Accordingly, FGFBP2+NKT cells expressed the highest levels of cytotoxic genes, such as GZMB, GZMH, PRF1, and GNLY, indicating that FGFBP2+NKT cells had the strongest tumor-killing effects." (PMID 38065972, 2023). "CD8-05-FGFBP2 cluster exhibited a CD8+ effector phenotype, upregulating genes involved in cytotoxicity and anti-tumor activity: FGFBP2, GNLY, FCGR3A, GZMH, PRF1, TGFBR3, and GZMB." (PMID 36350695, 2022). "In particular, six tumor cytotoxicity-related molecules (GZMA, GZMB, GZMH, IFNG, FASLG, and NKG7) from T cells had significantly higher levels in the BM than in PB." (PMID 40977909, 2022). "We observed that the expression of NKG7, GZMH, GZMA and GZMB in tumor-infiltrating CD8+ CTSW+ cytotoxic cells were significantly increased in female patients, indicating that these T cells have a stronger antitumor cytotoxic effect." (PMID 36172359, 2022). "In comparison to the adjacent non-tumor tissues, the CD56dimCD16hi NK cells within tumors showed a decrease in the expression of cytotoxic effector genes, such as PRF1 and most granzymes (GZMA, GZMH, and GZMM), except for GZMB." (PMID 38552055, 2024). "Selected genes are reflecting main anti-tumor immune pathways, such as Th1 signaling (IFNG, TBX21, CD8A/B, IL12B, STAT1 and IRF1), Th1 chemoattraction (CXCL9, CXCL10 and CCL5) and cytotoxic functions (GNLY, PRF1, GZMA, GZMB and GZMH)." (PMID 37726776, 2023). "Effector genes such as GZMB, GZMH and KLRG1 were the marker genes in clonotypes shared by all tissues, while the clonotypes present only in tumor showed upregulated T-cell exhaustion genes (HAVCR2, LAG3, CTLA4, TIGIT, PDCD1, and ICOS) and activation genes (SELL and TNFRSF9)." (PMID 36185254, 2022). "The increased expression of cytotoxic effector molecules GZMA, GZMB, GZMH, GZMM, GNLY, NKG7, and PRF178 but also of the thioredoxin function inhibitor TXNIP79, demonstrates a potent effector capacity to eliminate malignant cells and suppress tumor growth." (PMID 33602930, 2021). "As for T cell related cytotoxins, essential in tumor killing, stacked FPKM of 8 genes (PRF1, GZMM, GZMK, GZMH, GZMB, GZMA, FASLG, and FAS) demonstrated that these genes were more highly expressed 1.7-fold (P = 0.037) in IFNγ positive tumors compared to IFNγ negative tumors." (PMID 32265897, 2020).
tumor (continued). "Both subsets of CD8+ T cells from tumor samples expressed higher effector genes than nonmalignant samples, including chemokines (e.g., CCL5), cytotoxicity-associated genes (PRF1, GZMA, GZMB, GZMH), and proinflammatory cytokines (e.g., IL-32)." (PMID 34921160, 2021).
cancer (12 papers, 2014 to 2025). A tumor composed of atypical neoplastic, often pleomorphic cells that invade other tissues. "Our findings revealed a positive correlation between the expression levels of LAG3 and IFNG (R = 0.76, p < 0.001), PRF1 (R = 0.75, p < 0.001), FASLG (R = 0.75, p < 0.001), GZMH (R = 0.74, p < 0.001), NKG7 (R = 0.74, p < 0.001), and PDCD1 (R = 0.73, P < 0 0.001) in pan-cancer tissues." (PMID 38115039, 2023). "Interestingly, the expression levels of the cytotoxic effectors PRF1, GNLY, GZMA, GZMB and GZMH in CD8+ Tex subclusters were even richer than those in CD8+ Teff subclusters, which implied that CD8+ Tex cells still tended to respond to cancer cells." (PMID 35562760, 2022). "Notably, the GZMA CD4 T cell subset exhibited elevated expression of genes associated with effector and cytolytic functions in CD4 T cells, including GZMA, GZMH, GZMM, and PRDM1, while also showing moderate expression of anti-cancer-related genes such as IFNG, PRF1, and TNFSF10." (PMID 40959273, 2025). "We failed to found reports on GZMH and TNFSF13 expression in EVs of cancer cells." (PMID 35838333, 2022).
GZMH also shares sentences with these, for which no sentence is quoted: infection (11 papers); lipodystrophy (7); Hepatic steatosis (3); melanoma (3); glioma (2); Hyperinsulinemia (2); Insulin resistance (2); metabolic disease (2); osteosclerosis (2); Autoimmunity (1); bacterial sepsis (1); cardiomyopathy (1); Charcot-Marie-Tooth disease (1); chronic obstructive pulmonary disease (1); Cirrhosis (1); colorectal cancer (1); cutaneous leishmaniasis (1); cutaneous melanoma (1); dengue (1); Epileptic encephalopathy (1); familial partial lipodystrophy (1); generalized lipodystrophy (1); genetic diseases (1); heart failure (1); hepatocellular carcinoma (1); Hutchinson-Gilford progeria syndrome (1); hyperglycaemia (1); influenza (1); insomnia (1); intellectual deficiency (1).
A further 16 diseases each share a sentence with GZMH in 1 paper.